TSPYL6 (TSPY like 6)
Tractability: PROTAC: ubiquitination databases record sites on it.
Gene: Protein-coding gene on chromosome 2 (54,253,178 to 54,256,229, reverse strand). Ensembl gene ENSG00000178021.
Subcellular location (Human Protein Atlas): Nucleoplasm; Cytosol; Nucleoli
Gene Ontology:
Molecular function: protein binding
Biological process: nucleosome assembly
Cellular component: chromatin; nucleus
Genetic constraint (gnomAD): Loss-of-function variants: 0 observed, 0.84 expected, observed/expected ratio (o/e) 0, 90% interval 0 to 1.76. That is too few expected variants to judge how well the gene tolerates losing a copy. Missense variants: 695 observed, 560.62 expected, observed/expected ratio (o/e) 1.24, 90% interval 1.16 to 1.32. Synonymous variants: 255 observed, 227.68 expected, observed/expected ratio (o/e) 1.12, 90% interval 1.01 to 1.24.
Homologues: Orthologues: chimpanzee TSPYL6 (98% identical), macaque TSPYL6 (91% identical), zebrafish tspy (24% identical), Drosophila melanogaster Set (18% identical), Caenorhabditis elegans spr-2 (17% identical), Drosophila melanogaster Nap1 (12% identical), zebrafish nap1l4a (12% identical), Caenorhabditis elegans nap-1 (11% identical), Drosophila melanogaster CG3708 (11% identical), Drosophila melanogaster mil (9% identical). Paralogues in human: TSPYL1 (64% identical), TSPYL4 (50% identical), TSPYL5 (37% identical), TSPYL2 (37% identical), TSPY4 (22% identical), TSPY9 (22% identical), TSPY10 (21% identical), TSPY3 (21% identical), TSPY8 (21% identical), TSPY1 (21% identical), TSPY2 (21% identical), SETSIP (20% identical), and 6 more.
Diseases named in the same sentence as TSPYL6 in open-access papers:
TSPYL6 is named in the same sentence as 6 diseases in open-access papers, as found by Europe PMC text mining. Sharing a sentence is not in itself a finding about the gene and the disease. The quoted sentences say what the papers report.
breast carcinoma (1 paper, 2016). "We investigated the associations between single nucleotide polymorphisms (SNPs) in the testis-specific Y-encoded-like protein 6 (TSPYL6) gene and breast cancer (BC) susceptibility in the Han Chinese population." (PMID 27458158, 2016).
Stroke (1 paper, 2017). Sudden impairment of blood flow to a part of the brain due to occlusion or rupture of an artery to the brain. "Genetic polymorphisms of telomere-related genes such as ACYP2, TSPYL6, and TERT have been reported to be associated with stroke." (PMID 29383136, 2017).
TSPYL6 also shares sentences with these, for which no sentence is quoted: cancer (1 paper); lymph node metastasis (1); male infertility (1); tumor (1).